LINC02241 (long independently transcribed non-coding RNA 2241)
Gene: Long non-coding RNA gene on chromosome 5 (20,611,804 to 20,937,800, forward strand). Ensembl gene ENSG00000251629.
Diseases named in the same sentence as LINC02241 in open-access papers:
LINC02241 is named in the same sentence as 1 disease in open-access papers, as found by Europe PMC text mining. Sharing a sentence is not in itself a finding about the gene and the disease. The quoted sentences say what the papers report.
colorectal cancer (1 paper, 2024). A primary or metastatic malignant neoplasm that affects the colon or rectum. "One example is LINC02241, which we found expressed in 13.6% of the HCC samples and has been associated with poor prognosis in colorectal cancer." (PMID 38985879, 2024).